CCL20 (C-C motif chemokine ligand 20)
Diseases named in the same sentence as CCL20 in open-access papers (continued):
Sharing a sentence is not in itself a finding about the gene and the disease.
bladder cancer (1 paper, 2022). "We found that the transcription levels of CCL20 and CXCL14 in T24 and TCCSUP cells were significantly increased in the cisplatin treatment groups, and the correlation analysis showed that CCL20 and CXCL14 were significantly correlated with the cGAS-STING signal in the TCGA bladder cancer cohort." (PMID 36230972, 2022).
Cachexia (1 paper, 2025). Severe weight loss, wasting of muscle, loss of appetite, and general debility related to a chronic disease. "Models in the Sh‐vector+CCL20 group demonstrated significant weight loss and exhibited difficulty in food and water intake, indicating a cachexia‐like state." (PMID 40091357, 2025).
cervical intraepithelial neoplasia (1 paper, 2021). "In this context, we evaluated the distribution of CD45RA+ and CD45RO+ cells as well as CCR6+ and CCL20+ cells in intraepithelial (IE) and marginal stroma (MS) areas from cervical intraepithelial neoplasia (CIN) I–III, and CC as ‘immunoscore’ for HPV-induced CC outcome." (PMID 33888832, 2021).
childhood onset asthma (1 paper, 2020). Asthma that starts in childhood. "However, in PHA-stimulated T cells, the A allele of the reQTL (rs13034664), which was linked to increased risk of childhood-onset asthma, was associated with reduced CCL20 expression." (PMID 32724101, 2020).
Chlamydia infection (1 paper, 2021). "Chlamydia infection also induced a significant mRNA upregulation of the chemokines CXCL10, CXCL11, CCL20, and RANTES." (PMID 34684219, 2021).
cholestasis (1 paper, 2024). Impairment of the bile flow caused by obstruction within the liver, or outside the liver in the bile duct system. "CSA, a well-known inducer of cholestasis, downregulated gene expression of CYP7A1, CYP27A1, BAAT, HNF4A, and INSIG1, while it upregulated ACAT2 and CCL20 gene expression." (PMID 38953992, 2024).
Cholestatic liver disease (1 paper, 2023). "Consistent with the findings in a mouse model, patients with cholestatic liver disease showed elevated CCR6 expression, which linked CCL20 to biliary epithelial cells (BECs); however, these were considered as Th17-dominated." (PMID 37475963, 2023).
chronic GVHD (1 paper, 2012). "To further substantiate the relevance of the CCR6-CCL20 pathway in guiding migration of CD161-expressing T cells to GVHD-prone organs, we next determined CCL20 expression in situ in skin biopsies obtained from allo-SCT recipients who developed acute or chronic GVHD." (PMID 23226545, 2012).
chronic hepatitis B infection (1 paper, 2025). "This study has shown that the biomarkers GDF-15 and CCL-20 may be potential diagnostic biomarkers in detecting the presence of chronic hepatitis B, and the biomarkers CXCL-16, CCL-20, GDF-15, and CD8a may be potential diagnostic biomarkers in determining the severity of the disease." (PMID 41157623, 2025). "GDF-15 emerged as a robust and highly accurate marker for diagnosing chronic hepatitis B, while CCL-20 was found to be a dynamic indicator of inflammation induced by the virus." (PMID 41157623, 2025). "In our study, GDF-15 was found to be “excellent” at distinguishing patients with chronic hepatitis B infection from healthy individuals, while CCL-20 was found to be “good”." (PMID 41157623, 2025). "Our study investigated four biomarkers, providing promising results that are more comprehensive and detailed for diagnosing and staging chronic hepatitis B. Each biomarker captures a different aspect of the disease: GDF-15 (stress/injury), CCL-20 (inflammation), and CXCL-16/CD8a (T cell dynamics)." (PMID 41157623, 2025). "Our study has revealed valuable information that GDF-15, CCL-20, CXCL-16, and CD8a biomarkers, which can be measured quantitatively by a simple and cost-effective ELISA method, can be a tool that can support molecular testing (PCR) in the clinical management of chronic hepatitis B patients." (PMID 41157623, 2025).
chronic hepatitis C (1 paper, 2024). "Some therapeutical approaches, such as interferon therapy in chronic hepatitis C can cause elevation of the CCL20, lasting several weeks, which is why CCL20 was used as a prognostic marker during interferon therapy." (PMID 39435167, 2024).
chronic lymphocytic leukemia (1 paper, 2019). "Transcriptomic profiling from chronic lymphocytic leukemia patients successfully treated with CAR-T cells, revealed a general implementation of the IL-6/STAT3 signaling pathways, as indicated by increased production of IL-6, IL-17, IL-22, IL-31 and CCL20." (PMID 30999624, 2019).
chronic prostatitis (1 paper, 2024). An infectious or non-infectious chronic inflammatory process that affects the prostate gland. "The interplay between IL‐17A and CCL20 establishes a positive feedback loop, which might serve as a critical mechanism underpinning the development of chronic prostatitis, thus adding complexity to its treatment challenges." (PMID 38801403, 2024).
chronic sinusitis (1 paper, 2009). "Because MIP-3α/CCL20 is expressed in airway diseases, it is possible that MIP-3α/CCL20 functions as a chemotactic factor in the migration of Th17 cells and DCs into the sinus mucosa and nasal polyps in patients with chronic sinusitis." (PMID 23283206, 2009). "Considering our data, MIP-3α/CCL20 may play a role in upper airway diseases such as chronic sinusitis by recruiting Th17 cells and DCs into nasal polyps." (PMID 23283206, 2009).
contact dermatitis (1 paper, 2024). An inflammatory skin condition caused by direct contact between the skin and either an irritating substance or an allergen. "In the contact dermatitis mouse model, nuclear translocation of K17 facilitates the activation and nuclear translocation of signal transducer and activator of transcription 3 (STAT3) activating CCL20 production and CD8+ and CD4+ T cell trafficking to skin lesions." (PMID 38730319, 2024).
corneal disease (1 paper, 2012). "Further, in support of the contribution of IL-17A in the corneal disease that develops in the nude recipients, we measured the number of IL-17A, CCL20, MMP-3 and MMP-9 mRNA transcripts in this tissue." (PMID 22590618, 2012).
cutaneous melanoma (1 paper, 2021). A primary melanoma arising from atypical melanocytes in the skin. "In the current study, we measured diverse characteristics of tissue TAMs, including CCL20 and other cytokines by multicolor immunofluorescence and single-cell analysis, and correlated them with the clinical outcome of cutaneous melanoma patients." (PMID 34439098, 2021). "Consequently, we validated our previous pilot study in a large and independent patient cohort, using standard FFPE tissue sections instead of cryosections, and confirmed the role of CCL20, TNF, and VEGFA expression by TAMs in predicting clinical behavior of primary cutaneous melanoma patients." (PMID 34439098, 2021).
cutaneous squamous cell carcinoma (1 paper, 2024). "With respect to CCL20 inhibition, it has already been reported that CCL20 inhibition improves outcomes significantly in cutaneous squamous cell carcinoma patients receiving radiotherapy." (PMID 38730689, 2024).
cyst (1 paper, 2024). A sac-like closed membranous structure that may be empty or contain fluid or amorphous material. "Some factors (e.g., ICAM1, CCL20, PSME2, AXL) can also enhance proliferative signaling pathways (via MAPK/ERK, JNK, and JAK/STAT signaling, among others) that lead to cyst growth stimulation." (PMID 38385746, 2024).
delirium (1 paper, 2025). A disorder characterized by confusion; inattentiveness; disorientation; illusions; hallucinations; agitation; and in some instances autonomic nervous system overactivity. "Additionally, the expression of CCL20 was negatively associated with delirium." (PMID 40891141, 2025). "In our findings, we observed that elevated levels of CCL20, CCL25, and LIGHT were inversely associated with the likelihood of experiencing delirium." (PMID 40891141, 2025). "This suggests that an increase in the expression of this immune cell phenotype may lead to the occurrence of delirium, potentially mediated by the suppression of CCL20 expression." (PMID 40891141, 2025). "Second, our analysis revealed that CCL20 mediates the inhibitory proportion of CD127 on CD45RA−CD4 not Treg cells, regarding delirium at a rate of 9.78%." (PMID 40891141, 2025).
dengue (1 paper, 2020). "Further assessment of host factors revealed that cytokines such as CCL2, CCL5, CCL20 and CXCL1, as well as adhesion molecule ICAM-1, that are involved in leukocytes infiltration were expressed higher in dengue patients in comparison to healthy individuals." (PMID 32764789, 2020).
diabetic foot ulcer (1 paper, 2025). "Fig7B and 7C displays the expression levels of CCL20, CXCL13, FGFR2, FGFR3, PI3, PLA2G2A, and S100A8 across the six cell types.The results showed that the key pathogenic genes of diabetic foot ulcer were mainly involved in keratinocytes and neutrophils." (PMID 40749079, 2025).
dysplasia (1 paper, 2024). A usually neoplastic transformation of the cell, associated with altered architectural tissue patterns. "While all literature works consistently demonstrated that CCL20 up-regulation in invasive carcinoma, leading to a poor prognosis, the reasons behind its occurrence in dysplasia, particularly in association with NPDy, remain unknown." (PMID 39273632, 2024). "In laboratory experiments, isolated cells expressing CCL20 and CCR4, stimulated by IL-5 and IL-7, demonstrated an increased ability of CD8+ T cells to penetrate dysplastic cells, thereby improving therapeutic efficiency in fighting dysplasia." (PMID 39273632, 2024).
endometrial adenocarcinoma (1 paper, 2022). "The described mechanism was illustrated by treating FP-rich endometrial adenocarcinoma cells with recombinant CCL20, which resulted in a significant increase in the proliferation of adenocarcinoma cells." (PMID 35408440, 2022). "Induction of CCL20 by PGF-2α/FP signaling in an endometrial adenocarcinoma cell line was found to be dependent on intracellular signaling by Gq protein, epidermal growth factor receptor (EGFR), extracellular signal-regulated kinase (ERK), calcineurin, and nuclear factor of activated T cell (NFAT)." (PMID 35408440, 2022).
enteritis (1 paper, 2025). Inflammation of the small intestine. "Twelve-week-old A20ZF7Rag1–/– mice exhibited negligible intestinal inflammation and expressed levels of Il1b and Ccl20 similar to those in Rag1–/– mice, suggesting that adaptive lymphocytes are required for enteritis in A20ZF7 mice." (PMID 40892518, 2025).
extramammary Paget disease (1 paper, 2020). A malignant neoplasm in which there is infiltration of the skin by neoplastic large cells with abundant pale cytoplasm and large nuclei with prominent nucleoli (Paget cells). "More recently, we also reported the possible correlation between CCL20/IL-23/IL-17 axis in the development of extramammary Paget’s disease (EMPD)." (PMID 33178182, 2020).
Fever (1 paper, 2024). Body temperature elevated above the normal range. "We found significant differences in citrulline, REG3α, and CCL20 in patients with BSI, indicating more severe intestinal mucositis in BSI-related fever episodes, emphasizing the serious implications of bacterial translocation through an injured intestinal epithelium." (PMID 37919603, 2024).
fibromyalgia (1 paper, 2025). A chronic disorder of unknown etiology characterized by pain, stiffness, and tenderness in the muscles of neck, shoulders, back, hips, arms, and legs. "Elevated chemokines like CXCL5 and CCL20 are also observed in fibromyalgia, suggesting common immune activation mechanisms with ME/CFS." (PMID 40427027, 2025).
foot and mouth disease (1 paper, 2020). A viral infectious disease that results in infection in cattle and swine, has material basis in foot-and-mouth disease virus, which is transmitted by contaminated fomites, or transmitted by ingestion of food contaminated with infected meat or animal products. "Although two further studies investigated the use of CCL20 genetic adjuvantation of a HCV core plasmid DNA and of a foot-and-mouth disease vaccine, the IgG1 and IgG2a responses were assessed solely after Ag plus Montanide ISA 206 adjuvant boost, showing a Th1 profile." (PMID 31915263, 2020).
fungal keratitis (1 paper, 2023). "We identified 60 viral genes and 327 bacterial/fungal genes with an AUC of at least 0.9, among them MATR3, CXCL9, and KCNA3 for viral keratitis, and S100A8, CXCL8, and CCL20 for bacterial/fungal keratitis." (PMID 38274739, 2023). "MATR3 (AUC = 0.95), CXCL9 (AUC = 0.95), and KCNA3 (AUC = 0.90) were among the best candidate markers for viral keratitis, and S100A8 (AUC = 1), CXCL8 (AUC = 1), and CCL20 (AUC = 1) were among the best candidates for bacterial/fungal keratitis." (PMID 38274739, 2023).
gastric tumor (1 paper, 2023). "CCR6 is a non-promiscuous chemokine receptor that has only one known chemokine ligand, CCL20, and commonly exists on T cells and myeloid cells, the majority of gastric tumor–infiltrating immune cells in PpardTG mice." (PMID 37572185, 2023). "PPARδ dysregulation of Ccl20/Ccr6 axis promotes GAC carcinogenesis by remodeling gastric tumor microenvironment." (PMID 37572185, 2023). "Furthermore, Ccl20 protein levels increased in sera of PpardTG mice starting at the age preceding gastric tumor development and further increased with GAC progression as the mice aged." (PMID 37572185, 2023).
Gastrointestinal inflammation (1 paper, 2014). Inflammation of the alimentary part of the gastrointestinal system. "Increased CCL20 expression has been observed in gastrointestinal inflammation as well as skin inflammation." (PMID 24824519, 2014).
giant cell tumor (1 paper, 2019). A benign, intermediate, or malignant tumor that arises from the bone or soft tissue. "Stromal cell-derived CCL20 promotes tumor progression and osteolysis in giant cell tumors of bone." (PMID 31395078, 2019).
graft versus host disease (1 paper, 2024). An immune system disorder that occurs after allogeneic hematopoietic stem cell transplant and is a reaction of donor immune cells against host tissues. "Moreover, genes with similar expression patterns to CCL20 were primarily enriched in processes associated with graft-versus-host disease, primary immunodeficiency, antigen processing and presentation, TCR signaling, and NK cell mediated cytotoxicity." (PMID 38914792, 2024).
head and neck cancer (1 paper, 2024). A primary or metastatic malignant neoplasm affecting the head and neck. "On the other hand, Treg densities did not correlate with CCL20 levels, while they are described to be associated with increased in vitro Treg migration towards head and neck cancer cell lines." (PMID 39053947, 2024).
hepatitis B (1 paper, 2025). "We investigated the diagnostic properties of quantitative values of the biomarkers CCL-20, CXCL-16, CD8a, and GDF-15 in predicting hepatitis B using ROC curve analysis." (PMID 41157623, 2025).
hyperreactivity (1 paper, 2019). "We measured BAL CCL11 (eotaxin, an eosinophil chemoattractant), IL-23p19, IL-6, CXCL2 (pro-neutrophilic mediators), CCL20 (a lymphocyte chemoattractant), and IL-13 (known to prime smooth muscle cells for airway hyperreactivity)." (PMID 31572383, 2019).
immune complex disease (1 paper, 2020). "In summary, this report describes findings of inflammation in a 26-week toxicity study in cynomolgus monkeys with a humanized monoclonal antibody against CCL20, GSK3050002, which resembles immune complex disease." (PMID 32325480, 2020).
infectious conjunctivitis (1 paper, 2014). "Therefore, evaluation of local CCL20 expression in the ocular surface is thought to be important for understanding the pathologic features of inflammatory conjunctival diseases, including infectious conjunctivitis and allergic conjunctival diseases." (PMID 25172034, 2014).
infertile (1 paper, 2017). "To confirm that the currents induced by DEFB1 and CCL20 were genuinely mediated by CatSper channel, we performed patch-clamp experiments on sperm samples donated by an infertile male who carries a G to C mutation of CatSper2 in one allele and complete absence of CatSper2 in the other allele." (PMID 29207656, 2017).
invasive carcinoma (1 paper, 2024). A carcinoma that is not confined to the epithelium, and has spread to the surrounding stroma. "In invasive carcinoma, CCL20 has been reported to be up-regulated in association with fenretinide therapy (2.03-fold) and antifolate treatment, suggesting a synergistic action between CCL20 and fenretinide and an inverse correlation with thymidylate synthetase (TS)." (PMID 39273632, 2024).
ischemia (1 paper, 2025). A hypoperfusion of the BLOOD through an organ or tissue caused by a PATHOLOGIC CONSTRICTION or obstruction of its BLOOD VESSELS, or an absence of BLOOD CIRCULATION. "More recent data confirmed CCL20 upregulation in human AKI but observed protection from experimental ischemia–reperfusion AKI to CKD transition upon CCL20 blockade." (PMID 41226600, 2025).
Kawasaki disease (1 paper, 2024). A rare inflammatory disease characterized by an acute febrile, systemic, self-limiting, medium-vessel vasculitis primarily affecting children. "Plasma concentrations of ARG1, CCL20, CD163, CORIN, CXCL9, PCSK9 and ADAMTS2 were quantified in MIS-C (n = 22), Kawasaki disease (n = 23), definite bacterial (n = 28) and viral (n = 27) disease and healthy controls (n = 8)." (PMID 38359342, 2024).
kidney failure (1 paper, 2025). An acute or chronic condition that is characterized by the inability of the kidneys to adequately filter the blood. "From a metabolic point of view, transcriptionally, CCL20 was one of four chemokines and chemokine receptor hubs identified as upregulated in DKD and downregulated in more advanced kidney failure." (PMID 41226600, 2025).
laryngeal squamous cell carcinoma (1 paper, 2025). A squamous cell carcinoma that arises from the larynx. "A study on laryngeal squamous cell carcinoma has shown that chemokine receptors CCR6/CCR7 and their ligands CCL19/CCL20 synergically drive cervical lymph node metastasis of laryngeal squamous cell carcinoma through differential expression and Treg recruitment." (PMID 41445742, 2025).
Lewis lung carcinoma (1 paper, 2022). "Additionally, transfection of Lewis lung carcinoma cells with CCR6 caused local production of CCL20 in the lung and reduced the metastatic possibility in mice." (PMID 36612054, 2022).
lung squamous cell carcinoma (1 paper, 2025). "In the lung squamous cell carcinoma data set, the remaining genes, except IL1A and CCL20, also showed significant differences." (PMID 40016789, 2025).
lymphadenitis (1 paper, 2023). Acute or chronic inflammation of one or more lymph nodes. "CXCL9/MIG, CCL20, CCL23, CXCL10/IP-10, CXCL1, CXCL2, and CXCL8 significantly declined in our cohort of EPTB (48 TB pleuritis and 57 TB lymphadenitis) patients at both time points." (PMID 36635313, 2023).
mediastinal lymphoma (1 paper, 2007). "Recent findings suggest that expression of chemoattractants, such as CCL18, CCR6, and CCL20, on neoplastic epithelium in MNT can promote the recruitment of MALT, the emergence of monoclonal B cells, and, eventually, the subsequent development of mediastinal lymphoma." (PMID 17498299, 2007).
medullary breast carcinoma (1 paper, 2019). An infiltrating breast carcinoma with a relatively favorable prognosis. "The ligand for CCR6, CCL20 was higher in ductal and medullary breast carcinoma when compared to normal controls and other histological tissue types." (PMID 30850664, 2019).